ATXN1 (ataxin 1)
Diseases named in the same sentence as ATXN1 in open-access papers (continued):
Sharing a sentence is not in itself a finding about the gene and the disease.
spinocerebellar ataxia type 1 (continued). "Similarly, altered expression levels of BDNF have been observed in murine animal models of spinocerebellar ataxia type 1 (SCA1), which is a hNDD resulting from a mutation in the ATXN1 gene, causing progressive motor deficits." (PMID 39200370, 2024). "The integration of the different types of data allows users to easily compare them, as here shown for Ataxin-1, the polyQ protein involved in spinocerebellar ataxia type 1 (SCA1) disease." (PMID 36848492, 2023). "In spinocerebellar ataxia type 1 (SCA1), accumulation of polyglutamine-expanded (polyQ-expanded) ataxin-1 (ATXN1) causes neuronal toxicity." (PMID 35499073, 2022). "Spinocerebellar ataxia type 1 (SCA1) is an inherited neurodegenerative disease caused by mutations in the ATXN-1 gene which encode an abnormally expanded polyglutamine (polyQ) tract in the protein Ataxin-1." (PMID 35883691, 2022). "Spinocerebellar ataxia type 1 (SCA-ATXN1) is an autosomal dominant, neurodegenerative disease, caused by CAG repeat expansion in the ataxin-1 gene (ATXN1)." (PMID 34830553, 2021). "We have recently shown that ataxin-1—a polyglutamine protein implicated in the etiology of spinocerebellar ataxia type 1 (SCA1), Alzheimer’s disease (AD), and various types of cancer —exerts a B cell-mediated protective effect on the experimental autoimmune encephalomyelitis (EAE) model." (PMID 33478569, 2021). "Spinocerebellar ataxia Type 1 (SCA1) is caused by polyglutamine expansion of the ataxin-1 gene." (PMID 33409488, 2020). "In 1993, a group of investigators led by Huda Zoghbi and Harry Orr identified a heterozygous expansion of CAG repeat that encodes a polyglutamine (polyQ) tract in a novel gene, ATXN1, in a family with an autosomal-dominant cerebellar ataxia, now known as spinocerebellar ataxia type 1 (SCA1)." (PMID 32982927, 2020). "Patients with spinocerebellar ataxia type 1 express ataxin-1 with an extended polyglutamine (polyQ) tract that forms distinctive nuclear bodies." (PMID 32620905, 2020). "Spinocerebellar ataxia type 1 (SCA1) and HD are polyglutamine disorders caused by expansion of a CAG repeat within the coding regions of the Ataxin-1 and Huntingtin proteins, respectively." (PMID 32899411, 2020). "Pathological polyQ expansion, such as that in human Ataxin-1 (ATXN1), that causes spinocerebellar ataxia type 1 (SCA1), results in abnormal PPI." (PMID 31655597, 2019). "Ataxin-1 mutation, arising from a polyglutamine (polyQ) tract expansion, is the underlying genetic cause of the late-onset neurodegenerative disease Spinocerebellar ataxia type 1 (SCA1)." (PMID 30457570, 2018). "Exposing developing cerebellar Purkinje neurons (PNs) to mutant Ataxin1 (ATXN1) in 82Q spinocerebellar ataxia type 1 (SCA1) mice disrupts motor behavior and cerebellar climbing fiber architecture from as early as 4 weeks of age." (PMID 28979190, 2017). "In spinocerebellar ataxia 1 (SCA 1), the accumulation of the mutant ataxin-1 protein (ATXN1) causes loss of cerebellar Purkinje cells (PC) and dysfunction and degeneration in the cerebellum, brain stem, and spinal cord." (PMID 27570504, 2016). "Similarly, S-nitrosylation increases upon expansion of the polyQ tract of Ataxin-1, which is the cause of spinocerebellar ataxia type 1 (SCA1)." (PMID 27658206, 2016). "Spinocerebellar ataxia type 1 (SCA1) is a late onset autosomal dominant cerebellar ataxia, caused by CAG triplet repeat expansion in the ATXN1 gene." (PMID 25344417, 2014). "We discuss the paradigmatic example of ataxin-1 (Atx1), the protein responsible for neurodegenerative spinocerebellar ataxia type 1 (SCA1)." (PMID 24636457, 2014). "CHIP immunoreactivity has also been detected in the ataxin-1 nuclear inclusions (NIs) that are present in the brains of spinocerebellar ataxia type-1 patients." (PMID 24312598, 2013). "For example, the 20S proteasome localize at the site of mutant Ataxin-1 aggregation in neurons of spinocerebellar ataxia type 1 patients." (PMID 21998752, 2011).
spinocerebellar ataxia type 1 (continued). "For example, polyQ-expanded Huntingtin and Ataxin-1 are observed in Huntington's disease and spinocerebellar ataxia type-1 (SCA-1), respectively." (PMID 19389260, 2009). "Spinocerebellar ataxia type 1 (SCA1) is one of polyglutamine diseases, and is characterized as a progressive and autosomal dominant genetic disease, which is caused by an increasing number of CAG repeats in the ataxin-1 gene." (PMID 41377710, 2025). "Spinocerebellar ataxia type 1 (SCA1, MIM 164,400) and type 2 (SCA2, OMIM 183090) are autosomal dominant inherited diseases caused by an expansion of a highly polymorphic CAG repeat sequence within the coding region of the ATXN1 and ATXN2 gene, respectively." (PMID 38954239, 2024). "Strikingly, PRDM1 transcription factor was found to interact with 82Q ATXN1, the mutant protein in spinocerebellar ataxia type 1 (SCA1), and has been found to be expressed at the granule and Purkinje cells of the cerebellum during chicken embryonic and germline development." (PMID 38396267, 2024). "With Hsp70, sacsin may regulate the processing of ataxin-1 with polyglutamate expansion, especially the aberrant ataxin-1 degradation for protection against spinocerebellar ataxia-1." (PMID 35008978, 2022). "Like CAA interruptions in HTT, CAT interruptions of the ATXN1 CAG repeat in four spinocerebellar ataxia 1 subjects supported better tracking of age at onset with the uninterrupted CAG repeat size, but, because CAT specifies histidine, this was interpreted as an effect of polyglutamine length." (PMID 31398342, 2019). "A typical example of a pathogenic PrLD is that the trinucleotide is repeatedly amplified in the gene encoding ataxin 1 (ATXN1) in PrLDs and promotes aggregation of ATXN1, leading to polyglutamine protein production and, ultimately, to spinocerebellar ataxia type 1." (PMID 31022909, 2019). "Ataxin-1 is an ubiquitous protein well conserved in vertebrates, which is typically expressed in nuclear of neurons.Ataxin-1 plays an important role in protecting against aggregation of neurodegenerative spinocerebellar ataxia type 1." (PMID 27428326, 2016). "Moreover, miR-19, miR-101, miR-130 and lately miR-144 were found to co-regulate ATXN1, which is involved in spinocerebellar ataxia type 1 (SCA-1)." (PMID 23382970, 2013). "Spinocerebellar ataxia type 1 (SCA1) is a neurodegenerative disease marked by progressive motor deficits and Purkinje cell (PC) degeneration, driven by polyglutamine expansion in ataxin-1." (PMID 42113962, 2026). "Spinocerebellar ataxia type 1 (SCA1), spinocerebellar ataxia type 2 (SCA2) and Huntington disease are autosomal-dominant genetically determined neurodegenerative diseases, caused by the expanded CAG repeats (polyglutamine, polyQ) at the ATXN1, ATXN2 and HTT genes, respectively." (PMID 39974178, 2025). "Spinocerebellar ataxia type 1 (SCA1) is an autosomal dominant disorder characterized by degeneration of the cerebellum, brainstem, and spinal cord, caused by mutations in the ATXN1 (Ataxin-1) gene." (PMID 40563422, 2025). "To evaluate the efficacy of our algorithm, we predicted PTM-related PPIs of ataxin-1, a protein which is responsible for Spinocerebellar Ataxia type 1 (SCA1)." (PMID 40029919, 2025). "The investigation into the interaction between ataxin-1 and 14-3-3 proteins in understanding Spinocerebellar Ataxia Type 1 (SCA1) has been explored." (PMID 38375509, 2024). "Spinocerebellar Ataxia Type 1 (SCA1) is caused by an expansion of CAG codons within the exons of the ATXN1 gene, which codes for ataxin-1 protein." (PMID 38921455, 2024). "Propagation of oligomeric-structured polyglutamine-expanded ataxin-1 (Atxn1[154Q]) has been reported in the cerebellum of a Spinocerebellar ataxia type 1 (SCA1) knock-in mouse to correlate with disease propagation." (PMID 34826062, 2022). "The polyglutamine (polyQ) tract form of ataxin-1 drives disease progression in spinocerebellar ataxia type 1 (SCA1)." (PMID 36198386, 2022).
spinocerebellar ataxia type 1 (continued). "The expanded polyglutamine (polyQ) tract form of ataxin-1 drives disease progression in spinocerebellar ataxia type 1 (SCA1)." (PMID 32620905, 2020). "In spinocerebellar ataxia 1 (SCA1) patients, the mutant ATXN1 gene contains CAG repeats that encode an expanded polyglutamine (polyQ) region, and the formation of distinct nuclear “inclusions” of these polyQ-ataxin-1 proteins in SCA1 patients and transgenic mice." (PMID 32005838, 2020). "Spinocerebellar ataxia type 1 (SCA1), a condition resulting from the expansion of a polyglutamine tract in ataxin-1, results in neurodegeneration in the cerebellum and brain stem." (PMID 27376065, 2016). "We recently demonstrated that soluble oligomers play an important role in Spinocerebellar ataxia type 1 (SCA1), a neurodegenerative disease caused by expansion of a CAG repeat that encodes for glutamine (Q) in ataxin-1 (ATXN1)." (PMID 26673892, 2015). "For instance, individuals with expanded ataxin-1, the protein responsible for spinocerebellar ataxia type 1 (SCA1), but carrying histidine (CAT) interruptions were reported to be phenotypically normal, suggesting that interruptions could alter the polyQ properties and reduce the toxic effects." (PMID 23935513, 2013). "Atxn1L is a paralog of ATXN1 (aka ATAXIN1), originally identified in humans as the gene mutated in Spinocerebellar ataxia type 1 (SCA1)." (PMID 23555280, 2013). "miR-144 plays a central role in regulating the expression of ataxin 1 (ATXN1), a gene which is associated with spinocerebellar ataxia type 1 (SCA1)." (PMID 22482072, 2012). "Interestingly, in a conditional transgenic mouse model of spinocerebellar ataxia type 1, expression of polyglutamine-expanded Ataxin-1 protein during five days of cerebellar Purkinje cell development is sufficient for the loss of motor coordination in adult mice." (PMID 21695257, 2011). "Spinocerebellar ataxia type 1 (SCA1) was the first progressive autosomal dominant cerebellar ataxia to be genetically characterized; it is caused by an expanded CAG repeat in the coding region of the human ATXN1 gene." (PMID 40790250, 2026). "For instance, studies on spinocerebellar ataxia type 1 (SCA1) suggest a reciprocal relationship between PP2A and ataxin-1, whereby PP2A dephosphorylates ataxin-118 and ataxin-1 modulates PP2A activity and holoenzyme composition in Purkinje cells." (PMID 41509924, 2026). "Spinocerebellar ataxia type 1 (SCA1), an autosomal dominant neurodegenerative disease, is one of the neurodegenerative diseases caused by expansion of a CAG trinucleotide tract that encodes a polyglutamine stretch in the resulting ataxin-1 (ATXN1) protein." (PMID 38512434, 2024). "Using the ATXN1[82Q] model of spinocerebellar ataxia type 1 (SCA1), we explored the hypothesis that regional differences in Purkinje neuron degeneration could provide novel insights into selective vulnerability." (PMID 32964235, 2020). "Spinocerebellar ataxia type 1 (SCA1) is a dominantly inherited and fatal neurodegenerative disease resulting from an overexpansion of CAG repeats within the Ataxin-1 (ATXN1) gene." (PMID 30718999, 2018). "Moreover, ATXN1 regulates the cerebellar bioenergetics proteome through the GSK3b-mTOR pathway, which is altered in spinocerebellar ataxia type 1 (SCA1), an autosomal dominant neurodegenerative disorder." (PMID 29212253, 2017). "Ataxin-1 (ATX1) is the protein responsible for the currently incurable spinocerebellar ataxia type 1 (SCA1), a dominant neurodegenerative misfolding disease characterised by ataxia, progressive motor deterioration and degeneration of selected neuronal subtypes." (PMID 24155902, 2013). "Interestingly, both FOX-1 and FOX-2, also known as A2BP1 (ataxin-2 binding protein 1) and RBM9 (RNA binding motif protein 9), have been identified as interaction partners of ataxin-1 (ATXN1), which is implicated in spinocerebellar ataxia type 1 (SCA1)." (PMID 22666429, 2012).
spinocerebellar ataxia type 1 (continued). "Additionally, Spinocerebellar ataxia type 1 (SCA1), an adult-onset neurodegenerative disorder characterized by motor incoordination and cognitive decline, has been found in a close relationship with the modification of the ATXN1 protein." (PMID 38315329, 2024). "Spinocerebellar ataxia type 1 (SCA1) is a prototypical disease from the group of polyglutamine neurodegenerations, arising from the expansion of CAG repeats in the ATXN1 gene." (PMID 41463080, 2025). "In spinocerebellar ataxia type 1 (SCA1), a CAG repeat expansion in the ataxin 1 (ATXN1) gene changes the localization of ATXN1 protein." (PMID 36940239, 2023).
Ataxia (58 papers, 2007 to 2025). Ataxia refers to impaired coordination of voluntary muscle movement. "Pumilio is known to destabilize Atxn1 mRNA, and its haploinsufficiency increases Atxn1 protein levels causing ataxia in mice." (PMID 34165550, 2021). "Among the significant associations identified, SNP rs16879003 resides in the ATXN1 gene, a member of the spinocerebellar ataxia (SCA) family." (PMID 29221444, 2017). "Subsequently, high throughput screens for protein–protein interactions revealed that UbcM2 interacts with the Huntington’s Disease proteins HTT and RNF2 and with the spinocerebellar ataxia-associated protein ATXN1." (PMID 26566974, 2015). "In this regard, genetic causes could have a significant role considering the recent observation that genetic risk alleles for ALS also include spinocerebellar ataxia-associated genes (i.e., ATXN1, ATXN2)." (PMID 36370302, 2023). "Conversely, ATXN1(82Q) mice reveal severe ataxia and progressive Purkinje cell loss." (PMID 31892274, 2019). "Interestingly, in 3 week old 30Q (D776) mice (where fewer CAG repeats are overexpressed but a point mutation enhances nuclear translocation of ATXN1) CFs are also retracted and these mice exhibit ataxia 3 weeks later." (PMID 28979190, 2017). "Indeed, Ataxin-1, as well as another ataxia-associated protein, Ataxin-3, have been linked to the retinoic acid-related orphan nuclear receptor alpha (RORα) pathway, which is critical for cerebellar development." (PMID 26136256, 2015). "Notably, GWAS data indicate that UbcM2 can interact with ATXN1, a protein linked to spinocerebellar ataxia (SCA)." (PMID 26566974, 2015). "The functional interactions between Ataxin-1 and Ataxin-2 described here mechanistically tie these two proteins and point to previously unknown pathogenic links between two inherited ataxias." (PMID 18166084, 2007). "Mutant ataxin-1 accumulates in Purkinje cell nuclei, forming intranuclear inclusions and producing progressive cerebellar ataxia." (PMID 41463080, 2025). "Studies have shown that intermediate STR expansions in the spinocerebellar ataxia (SCA) genes, ATXN1 (SCA1) and ATXN2 (SCA2) are associated with ALS risk." (PMID 40012994, 2025). "Many forms of spinocerebellar ataxia, which are among the most common hereditary ataxias, are caused by trinucleotide repeat expansions in several genes (FXN, ATXN1, ATXN2, ATXN3)." (PMID 41010014, 2025). "While the C9orf72 STR expansion is the most established genetic basis for ALS and FTD, intermediate STR expansions within the Spinocerebellar ataxia (SCA) genes ATXN1 (SCA1) and ATXN2 (SCA2) have emerged as noteworthy contributors to ALS susceptibility." (PMID 39039334, 2024). "In patients with cerebellar signs, 6 of 9 were screened for the common spinocerebellar ataxia genes including ATXN1 (SCA 1), ATXN 2 (SCA2), ATXN3 (SCA3) and ATXN7 (SCA7)." (PMID 39113437, 2024). "SCA1 is caused by expansion of a CAG repeat in the ataxin 1 gene (ATXN1), yielding a large glutamine repeat in the protein, which causes cerebellar and brain stem degeneration and ataxia." (PMID 34445199, 2021). "More than 39 uninterrupted CAG repeats in the ATXN1 gene causes SCA1, with the initial symptoms of ataxia, defined by movement and balance deficits, normally presenting in the patient’s mid-thirties." (PMID 29975753, 2018). "Apart from key ataxia proteins like ataxin-1 or ataxin-3, this degradation also includes proteins involved in motor neuron disease such as SOD1 proteins." (PMID 24742043, 2014). "For instance, non-pathogenic alleles of the spinocerebellar ataxia-related genes ATXN1 (SCA1; OMIM 164400) and ATXN2 (SCA2; OMIM 183090) have tracts interrupted by 1–3 CAT (His) codons in ATXN1 and CAA (Gln) codons in ATXN2." (PMID 39125760, 2024). "We hypothesized that the gradual aggregation of ATXN1(Q82) into insoluble inclusions in MSCs may have similar molecular characteristics to progressive ataxia observed in B05 mice with aging." (PMID 32992839, 2020).